OLFM4 (olfactomedin 4)
Description:
May promote proliferation of pancreatic cancer cells by favoring the transition from the S to G2/M phase. In myeloid leukemic cell lines, inhibits cell growth and induces cell differentiation and apoptosis. May play a role in the inhibition of EIF4EBP1 phosphorylation/deactivation. Facilitates cell adhesion, most probably through interaction with cell surface lectins and cadherin.
Synonyms: OLM4; hGC-1; GW112; OlfD; GC1; pDP4; UNQ362; bA209J19.1; hOLfD
Tractability: Antibody: its Gene Ontology location is reachable by antibodies, with high confidence; UniProt places it where antibodies can reach, with medium confidence; UniProt predicts a signal peptide or a membrane-spanning region; the Human Protein Atlas places it where antibodies can reach.
Gene: Protein-coding gene on chromosome 13 (53,028,813 to 53,052,057, forward strand). Ensembl gene ENSG00000102837.
Subcellular location: Secreted, extracellular space; Mitochondrion
Subcellular location (Human Protein Atlas): Nucleoplasm; Plasma membrane; Cytokinetic bridge; Cytosol; Predicted to be secreted
Pathways (Reactome):
Immune System: Neutrophil degranulation
Gene Ontology:
Molecular function: cadherin binding; protein binding; structural molecule activity
Biological process: positive regulation of substrate adhesion-dependent cell spreading; signal transduction
Cellular component: azurophil granule; cytosol; extracellular exosome; extracellular region; nucleoplasm; perinuclear region of cytoplasm; plasma membrane; protein-containing complex; secretory granule; specific granule; specific granule lumen; tertiary granule lumen; mitochondrion
Genetic constraint (gnomAD): Loss-of-function variants: 28 observed, 33.01 expected, observed/expected ratio (o/e) 0.85, 90% interval 0.63 to 1.16. The upper end of that interval is the gene's LOEUF score, 1.16, which puts it in group 5 of 6, group 1 being the genes least tolerant of losing a copy. Missense variants: 594 observed, 650.29 expected, observed/expected ratio (o/e) 0.91, 90% interval 0.85 to 0.98. Synonymous variants: 255 observed, 250.56 expected, observed/expected ratio (o/e) 1.02, 90% interval 0.92 to 1.13.
Homologues: Orthologues: chimpanzee OLFM4 (99% identical), macaque OLFM4 (93% identical), dog OLFM4 (77% identical), pig OLFM4 (71% identical), mouse Olfm4 (70% identical), guinea pig OLFM4 (70% identical), rat Olfm4 (70% identical), tropical clawed frog olfm4 (44% identical), zebrafish olfm4.1 (33% identical), zebrafish olfm4.2 (32% identical). Paralogues in human: OLFM1 (24% identical), OLFM2 (23% identical), OLFML2A (22% identical), OLFML2B (21% identical), OLFM3 (20% identical), MYOC (19% identical), OLFML3 (17% identical), GLDN (16% identical), OLFML1 (15% identical).
Diseases named in the same sentence as OLFM4 in open-access papers:
OLFM4 is named in the same sentence as 136 diseases in open-access papers, as found by Europe PMC text mining. Sharing a sentence is not in itself a finding about the gene and the disease. The quoted sentences say what the papers report.
gastric cancer (32 papers, 2012 to 2025). A primary or metastatic malignant neoplasm involving the stomach. "Knockdown of OLFM4 promotes the migration of gastric cancer cells through NF-κB, and low expression is associated with lymph node metastases in early gastric cancer." (PMID 40925382, 2025). "OLFM4 was closely associated with digestive diseases, whose dysregulation had been detected in gastrointestinal malignancies, including gastric cancer, colorectal cancer, pancreatic cancer, and gallbladder cancer." (PMID 37667332, 2023). "Comparison of normal gastric epithelial cells and tissues vs. gastric cancer cell lines and tumors, and is miR-486-5p is a combinatorial risk factor alongside olfactomedin-4 (OLFM4) and fibroblast growth factor 9 (FGF9)." (PMID 34425560, 2021). "Similar results were observed that high expression of OLFM4 was significantly associated with better overall survival as well as progression-free survival in gastric cancer patients." (PMID 27294866, 2016). "Increased serum levels of OLFM4 have been proposed as diagnostic markers of early stages of gastric cancer and colorectal cancer." (PMID 25364714, 2014). "Relatively little is known regarding the tumor growth and apoptosis underlying gastric cancer-specific OLFM4 expression." (PMID 22471589, 2012). "Low expression of OLFM4 promoted lymph node and distant metastasis resulting in a poor prognosis of triple-negative breast cancer patients and low expression of OLFM4 in early gastric cancer was associated with lymph node metastasis." (PMID 36922564, 2023). "In gastric carcinoma OLFM4 was also associated with metastasis." (PMID 31283789, 2019). "Most studies to date have focused on OLFM4, which has been associated with some of the most prevalent malignancies, including gastric cancer, pancreatic cancer, colon, lung and breast cancer, colorectal adenomas and liver metastases of colorectal origin, endometriosis, and cervical cancer." (PMID 25364714, 2014). "Early gastric cancers with high OLFM4 expression may have an increased risk of metastasis to the lymph nodes, and combining OLFM4 expression with tumor size and differentiation status may result in better classification of early gastric cancer patients." (PMID 36081904, 2022). "Here, we showed that knock-down of OLFM4 effectively enhanced cell apoptosis in response to H2O2 or TNF α stimulation in MKN45 as well as SGC-7901 cells, suggesting blocking OLFM4 may increase the susceptibility of gastric cancer cells to the presence of H2O2 or TNF α." (PMID 22471589, 2012). "OLFM4 is mainly expressed in the digestive system as a marker for intestinal stem cells and is upregulated in several types of cancers, including gastric cancer." (PMID 40925382, 2025). "OLFM4 is reported to be upregulated in gastric cancer, and is reversely correlated with NF-κB/IL-8 pathway in gastric cancer." (PMID 36474268, 2022). "In gastric cancer, upregulation of OLFM4 has been shown to promote tumor progression and metastasis." (PMID 34885041, 2021). "Clinical studies to examine the association of mRNA expression of GREM1, BAG2, OLFM4, TRIP6 and MAGE-A9 and OS in patients with intestinal or diffuse subtype of gastric cancer using different chemotherapeutic agents need to be done." (PMID 34885041, 2021). "In gastric cancer cells, it was found that depletion of the OLFM4 gene inhibited cell growth and increased sensitization to hydrogen peroxide, and TNFα induced apoptosis." (PMID 34912753, 2021). "OLFM4 is involved in cell adhesion and migration and also has an anti-apoptotic effect in tumor cells including gastric cancer cells." (PMID 34885041, 2021). "Only one previous study studied the role of OLFM4 in early cancer (pT1a and pT1b gastric cancer, n = 105) and concluded that low OLFM4 expression was independently predictive for LNM." (PMID 31283789, 2019). "In gastric cancer, low OLFM4 expression is correlated with poor differentiation grade and the presence of LNM, as well as with adverse survival." (PMID 31283789, 2019).
gastric cancer (continued). "For example, the anti-oncogenic activity of miR-486 is probably related to targeting and suppressing OLFM4 in gastric cancer." (PMID 31528235, 2019). "The results recommend that expression profiling of OLFM4 can be used for diagnosis of gastric cancer, and OLFM4 seems to be used as a biomarker for the diagnosis of gastric cancer." (PMID 29511474, 2017). "In current study, the OLFM4 expression level in Iranian patients with gastric cancer was evaluated by using the Real Time-PCR method." (PMID 29511474, 2017). "In gastric cancer, the down-regulation of miR-486-5p was confirmed in tissue and cell lines and OLFM4 was identified as the target." (PMID 28030794, 2017). "Patients with well-differentiated gastric cancer and higher OLFM4 expression have a five-year survival rate higher than patients with poorly differentiated cancer." (PMID 26871282, 2016). "In vitro studies revealed that knockdown of OLFM4 promoted the migration of gastric cancer cells through activating the NF-κB/interleukin-8 axis." (PMID 27294866, 2016). "miR-486 targets Pim-1 kinase in lung cancer, OLFM4 in gastric cancer, CLDN10 and CITRON in hepatocellular carcinoma, and plasminogen activator inhibitor-1 in human myxoid liposarcoma." (PMID 26871282, 2016). "We next explored the relationship between OLFM4 expression and overall survival of gastric cancer patients in our cohort." (PMID 27294866, 2016). "OLFM4 expression was also significantly reversely correlated with IL-8 expression in gastric cancer tissues." (PMID 27294866, 2016). "In our study, we also verified the negative correlation between OLFM4 and NF-κB activation in transformed gastric cancer cells, and found that NF-κB/IL-8 pathway was critical for OLFM4 depletion-induced migration of cancer cells." (PMID 27294866, 2016). "OLFM4 expression is increased in cancers of the stomach, colon, pancreas, lung, and breast, and OLFM4 expression is correlated with tumor differentiation and prognosis." (PMID 26871282, 2016). "Results indicated that administration of Reparixin, an inhibitor of IL-8 receptor, blocked the migratory ability in OLFM4-depleted gastric cancer cells." (PMID 27294866, 2016). "Results demonstrated that high expression of OLFM4 in tumor tissues showed a survival advantage for gastric cancer patients at all stages." (PMID 27294866, 2016). "miR-486-5p is enriched in muscle tissue, and miR-486-5p targets OLFM4 thereby playing a tumor-suppressive role in gastric cancer." (PMID 26871282, 2016). "OLFM4, olfactomedin 4, has been reported to be over-expressed in various cancers including gastric cancer but also colon, breast, and lung cancers, and has been proposed as a potential serum biomarker of gastric cancer." (PMID 25970782, 2015). "Gene-expression data have revealed downregulation of the OLFM4 gene in prostate cancer, colon cancer, and leukemia, whereas OLFM4 expression was found to be upregulated in gastric cancer and pancreatic cancer." (PMID 26581960, 2015). "In previous report, positive expression of OLFM4 was already found to be correlated with age in patients with gastric cancer, which is consistent with our result." (PMID 25970782, 2015). "Expression of OLFM4 (olfactomedin 4), an antiapoptotic factor known to act as a marker for colorectal and gastric cancer, was also decreased in athletes, perhaps denoting a potential benefit of exercise training against these tumor types." (PMID 24643011, 2014). "Depletion of Olfm4 in gastric cancer cells has been reported to suppress proliferation and sensitise cancer cells to apoptosis." (PMID 25010414, 2014). "Reduced expression of the OLFM4 gene inhibits cell growth and increases sensitization to hydrogen peroxide and tumor necrosis factor alpha-induced apoptosis in gastric cancer cells." (PMID 23430930, 2013). "Based on the present data, it is conceivable that up-regulated OLFM4 enables gastric cancer cells to resist apoptosis induction by decreasing the susceptibility to anticancer drugs." (PMID 22471589, 2012).
gastric cancer (continued). "To determine the role of OLFM4 in gastric cancer cell growth, we investigated the effect of OLFM4-siRNA on the cell growth at 1-5 day time point by WST-1 assay." (PMID 22471589, 2012). "Xenograft tumor model in vivo also implies that decreased OLFM4 can inhibit the tumor growth of human gastric cancer cells." (PMID 22471589, 2012). "To date, however, very limited data concerning the role of OLFM4 in the cell growth and apoptosis profiles of gastric cancer cells has been published." (PMID 22471589, 2012). "In the present study, we analyzed OLFM4 protein expression in gastric cancer cells and normal human gastric epithelial GES-1 cells by western blotting." (PMID 22471589, 2012). "To further examine the importance of OLFM4 in the tumorigenesis of gastric cancer cells in vitro, we carried out anchorage-independent growth assays and found SGC-7901 and MKN45 cells expressing HK controls grew well in soft agar, forming distinct colonies." (PMID 22471589, 2012). "Our study suggests that depletion of OLFM4 significantly inhibits tumorigenicity of the gastric cancer SGC-7901 and MKN45 cells." (PMID 22471589, 2012). "OLFM4 protein expression pattern was investigated in gastric cancer BGC-823, HGC-27, SGC-7901, MKN28, MKN45 cells and normal GES-1 control cells." (PMID 22471589, 2012). "Taken collectively, both in vitro and in vivo experiments suggest that OLFM4 knockdown inhibits the growth of gastric cancer cells." (PMID 22471589, 2012). "OLFM4 is found to be frequently up-regulated in many types of human tumors including gastric cancer and it was believed to play significant role in the progression of gastric cancer." (PMID 22471589, 2012). "Using plasmid-mediated short hairpin RNA (shRNA), we inhibited OLFM4 expression in the gastric cancer SGC-7901 and MKN45 cells to observe cell proliferation, cell cycle phase, apoptosis in vitro and to assess its tumorigenic capacity in vivo." (PMID 22471589, 2012). "Recently accumulating data demonstrated OLFM4 is frequently overexpressed in many types of human tumors including gastric cancer, and it was believed to play a crucial role in the development and progression of gastric carcinogenesis." (PMID 22471589, 2012). "The aim of this study is to examine the role of gastric cancer-specific expression of OLFM4 in cell growth and apoptosis resistance." (PMID 22471589, 2012). "In particular, SGC-7901 and MKN45 cells expressed relative high level OLFM4 protein than other gastric cancer cells and GES-1 cells." (PMID 22471589, 2012). "Blocking OLFM4 expression can sensitize gastric cancer cells to H2O2 or TNF α treatment by increasing caspase-3 dependent apoptosis." (PMID 22471589, 2012). "In all two gastric cancer cell lines, the growth of OLFM4 knock down cells was significantly reduced compared with HK control cells from day 3 (P < 0.01)." (PMID 22471589, 2012). "Taken together, the present study provides evidences that the elimination of OLFM4 expression in gastric cancer SGC-7901 and MKN45 cells inhibits tumorigenicity both in vitro and in vivo by regulating cell cycle progression not involving apoptosis." (PMID 22471589, 2012). "In our present works, we directly investigated OLFM4 protein expression pattern in gastric cancer cells and normal GES-1 cells." (PMID 22471589, 2012). "In other words, OLFM4 knock down enhanced H2O2 or TNF α-induced apoptosis in gastric cancer cells, indicating deletion of OLFM4 made SGC-7901 and MKN45 cells more sensitive to treatment of H2O2 or TNF α." (PMID 22471589, 2012). "Thus, OLFM4 can be used as a novel biomarker in gastric cancer recognition and progression in early stages." (PMID 29511474, 2017). "The results of Iranian patients with gastric cancer confirmed the findings of other countries about the overexpression of OLFM4 in gastric cancer tumors, which indicates that this gene can serve as a potential biological marker for prediction, diagnosis, and treatment of GC." (PMID 29511474, 2017).
gastric cancer (continued). "OLFM4 was differentially expressed in a panel of gastric cancer cell lines." (PMID 27294866, 2016). "We next evaluated the potential effect of OLFM4 on the migration of gastric cancer cells." (PMID 27294866, 2016). "The metastatic mechanism of OLFM4 in gastric cancer was also investigated." (PMID 27294866, 2016). "Knockdown of OLFM4 showed little effect on the viability of gastric cancer cells." (PMID 27294866, 2016). "As OLFM4 expression was reported to be associated with gastric cancer differentiation, we next investigated whether OLFM4 had an effect on morphology of gastric cancer cells." (PMID 27294866, 2016). "We next explored how OLFM4 modulated the migration of gastric cancer cells." (PMID 27294866, 2016). "OLFM4 protein definitely expresses in all these gastric cancer cells and GES-1 cells." (PMID 22471589, 2012). "A combination strategy based on OLFM4 inhibition and anticancer drugs treatment may provide therapeutic potential in gastric cancer intervention." (PMID 22471589, 2012). "Our present works demonstrate that OLFM4 plays an essential role in gastric cancer tumorigenesis." (PMID 22471589, 2012). "Moreover, suppression of OLFM4 enhances caspase-3 dependent apoptosis in response to H2O2 or TNF α in human gastric cancer cells." (PMID 22471589, 2012). "First, as recent studies suggested, a cell or tissue specific role of OLFM4 (gastric cancer cells and pancreatic cancer cells) may be a persuasive explanation for this discrepancy." (PMID 22471589, 2012). "However, in another group of gastric cancer cases of all stages, low expression of OLFM4 was significantly related to poor differentiation (P=0.011), diffuse and mixed type (P=0.031), higher invasion depth (P=0.004), LNM (P=0.008) as well as late TNM stage (P=0.002)." (PMID 27294866, 2016). "For example, OLFM4 expression is enhanced in gastric cancer (GC), with 56% of GC cases positive for OLFM4." (PMID 24495253, 2014). "By understanding the role of OLFM4 in tumor growth and apoptosis resistance, it may be possible to develop a perspective strategy based on a combination of OLFM4 inhibition and anticancer drugs treatment in gastric cancer intervention." (PMID 22471589, 2012). "In gastric cancer, EBV infection promotes the upregulation and secretion of OLFM4 by potentiating the cGAS-STING pathway, eventually augmenting the cancer progression." (PMID 40002690, 2025). "Overexpression of BAG2, GREM1, OLFM4, and TRIP6 in the diffuse subtype of gastric cancer on IHC as compared to the intestinal subtype suggests a role of these proteins in the pathogenesis and progression of the diffuse subtype." (PMID 34885041, 2021). "The candidate proteins BAG2, GREM1, OLFM4, TRIP6, and MAGE-A9, were shown to be differentially expressed and validated using IHC in the diffuse and intestinal subtypes of gastric cancer." (PMID 34885041, 2021). "In our study we focused on the expression changing level of OLFM4 and COL11A1 in Iranian patients to identify role of these genes in gastric cancer progression." (PMID 29511474, 2017). "In most cases, OLFM4 and COL11A1 are found to be up-regulated in many types of human cancers including gastric cancer." (PMID 29511474, 2017). "In addition, administration of recombinant OLFM4 protein blocked cellular migration in both wild-type and OLFM4-depleted cells, implying that tumor-derived OLFM4 may inhibit the migratory activity of gastric cancer cells in an autocrine-dependent manner." (PMID 27294866, 2016). "The seven RNAs upregulated in gastric cancer were CLDN18, EPCAM, REG4, BBC3, OLFM4, PPARG, and CDH17, while the two downregulated genes were IFITM1 and HIF1A." (PMID 22929309, 2012). "Indeed, OLFM4, a target gene of NF-κB pathway, has also shown a negative feedback effect on H. pylori infection-induced NF-κB activation in HEK 293 T cells, indicating the regulatory pathways controlled by OLFM4 in gastric cancer could be involved in a very complex and intricate network." (PMID 22471589, 2012).